LEP (leptin)
Diseases named in the same sentence as LEP in open-access papers (continued):
Sharing a sentence is not in itself a finding about the gene and the disease.
Hypertension (continued). "Research has shown that hypertensive patients have higher circulating leptin levels and that leptin can be used as a predictor of new-onset hypertension." (PMID 33265898, 2020). "Central administration of leptin mimicked HFD sensitization of ANG II-induced hypertension while central leptin antagonist prevented the sensitization." (PMID 32760236, 2020). "Zohreh Nowzari20 searched for associations between LEP and LEPR gene polymorphisms and CADsusceptibility and hypertension among Iranians." (PMID 32049202, 2020). "Recently, Shin and collaborators have shown that leptin induces hypertension by elevating the blood pressure in lean mice, when administered subcutaneously, and in LepRb-deficient db/db mice via the expression of leptin receptors in CB." (PMID 32698380, 2020). "We have shown that VSMCs produce the leptin protein and that its production is significantly upregulated by mimicking hypertension." (PMID 32566092, 2020). "Our group proposed that CB induces hypertension by the stimulation of leptin signaling in the glomus cells, and the downstream activation of transient receptor potential melastatin 7 (TRPM7) channels." (PMID 32698380, 2020). "In support of this conjecture, elevation in serum leptin in obese rodents, induced by a high-fat diet, developed high blood pressure through a CNS mechanism." (PMID 33114326, 2020). "Central SNS activation, induced by hyperactivity of leptin and the preproopiomelanocortin pathway, is also related to obesity and hypertension." (PMID 31236708, 2019). "Both male and female hypoxia-exposed offspring demonstrated evidence of hypertension, hypercholesterolemia, and increased leptin concentrations." (PMID 30718791, 2019). "The increased leptin levels lead to hypertension in mouse models and have been shown to increase blood pressure through sympathetic activation and by influencing nitric oxide synthesis." (PMID 31737362, 2019). "It has also been demonstrated in an animal model (female mice) that leptin induced hypertension and endothelial dysfunction via aldosterone-dependent mechanism." (PMID 31737362, 2019). "Leptin had been found to able to trigger hypertension in various animal and clinical studies, thus can exacerbate atherosclerosis in cardiovascular disease." (PMID 29304064, 2018). "In contrast, the MHO individuals with high leptin levels and high L:A ratio were significantly more likely to developing hypertension (RR 11.04; 95% CI, 1.18–103.35 and RR 9.88; 95% CI, 1.11–87.97, respectively)." (PMID 29093301, 2018). "Several studies showed that plasma leptin is elevated in hypertensive patients and it was positively correlated with the development of hypertension in humans." (PMID 29675134, 2018). "Meanwhile, alpha antagonist, through the inhibition of leptin-induced sympathetic tone, was proved to reverse this high blood pressure in rat." (PMID 29304064, 2018). "Multivariate analysis, adjusted for sex, adiponectin, the liver-to-spleen ratio, DGLA and HOMA-R, revealed age, BMI, serum leptin level, the presence of hypertension and the cystatin C level to be positively related to EAT values." (PMID 28922364, 2017). "In hypertension, leptin induces endothelial nitric oxide synthase expression and vasodilation by the direct action of leptin on vascular endothelial cells." (PMID 28591164, 2017). "Leptin, whose serum concentration positively correlates with waist circumference, emphasizes the significance of abdominal obesity in the pathology of arterial hypertension and glucose metabolism disorders." (PMID 29225622, 2017). "We have shown that blood vessels under mechanical stretch, a model mimicking hypertension, have the ability to produce and secrete leptin protein and leptin receptor mRNA expression." (PMID 27746739, 2016). "Leptin levels increased in obese pregnant women, showing a positive correlation with maternal BMI, hyperglycemia and hypertension and an inverse correlation with newborn abdominal circumference." (PMID 27651836, 2016).
Hypertension (continued). "A counterintuitive effect of leptin is present in its reinforcement of sympathetic action on the adrenocortical system, but an important link to hypertension." (PMID 27147943, 2016). "Rodents exposed to intravenous infusion and intracerebroventricular leptin administration demonstrated increased arterial pressure and heart rate, while blocking the adrenergic system diminished leptin-induced hypertension." (PMID 26064110, 2015). "Plasma leptin concentrations are elevated in cases of cardiovascular diseases, such as hypertension, congestive heart failure, and myocardial infarction." (PMID 26064110, 2015). "Here too, however, the evidence for a role of leptin in hypertension is relatively strong in animal studies." (PMID 26617526, 2015). "The current study sought to delineate the possible role of increased mechanical stretch (hypertension) on leptin protein synthesis in VSMCs and on early time points of leptin release (1, 3, 6, 18 h)." (PMID 26557089, 2015). "With respect to CVDs, leptin induces hypertension, atherosclerosis, myocardial infarction, vascular inflammation, VSMC hypertrophy and endothelial dysfunction." (PMID 25573199, 2015). "Accordingly, the present study was designed to determine the interaction between hypertension, leptin, and ROS and to identify their role in promoting vascular hypertrophy." (PMID 26557089, 2015). "Not only are leptin concentrations directly increased as a result of hypertension, leptin itself contributes to the development of hypertension." (PMID 26064110, 2015). "Leptin is currently thought to contribute to systemic hypertension by a combination of mechanisms including sympathetic nervous system activation, overproduction of endothelin-1 and decreased release of NO." (PMID 24499246, 2014). "The results are compatible with the notion of abnormal pulmonary endothelial function involving leptin and endothelin-1 control in systemic hypertension." (PMID 24499246, 2014). "The findings of this study nevertheless do point to a potential role for leptin in pregnancy-induced hypertensive disorders." (PMID 24167814, 2013). "Among adipocytokines specifically produced by fat tissue, leptin and adipokine play a central role in the genesis of hypertension and renal damage." (PMID 23320148, 2012). "Hyperleptinemia is known to participate in cardiac hypertrophy and hypertension, but the relationship between pressure overload and leptin is poorly understood." (PMID 23270329, 2012). "The role of leptin in hypertension has been previously detailed with leptin-mediated increases in BP being prevented by adrenergic blockade." (PMID 23251471, 2012). "Higher leptin concentrations are related to the increased sympathetic nerve activity and hypertension in the obese subjects." (PMID 22373492, 2012). "Our findings showed that HFD-fed rats exhibited a potent increase in serum leptin associated with a significant rise in angiotensin converting enzyme activity (ACE), key enzyme related to hypertension." (PMID 23258993, 2012). "In a human study, a correlation was seen between the serum concentration of leptin and blood pressure among patients with essential hypertension." (PMID 22642879, 2012). "Visceral and renal fat accumulation through consumption of a HFD leads to marked renal sympathetic activation, which is related to increased responsiveness to central sympathoexcitatory effects of leptin that contributes to the development of hypertension." (PMID 21235803, 2011). "The attenuation of this inhibitory effect of leptin in spontaneous hypertension appears to be due to a reduced NO bioavailability in VSMCs." (PMID 20592755, 2010). "Leptin, an adipose tissue hormone which regulates food intake, is also involved in the pathogenesis of arterial hypertension." (PMID 21286276, 2010). "Early postnatal overfeeding is known to induce cardiovascular and metabolic changes such as hypertension and central obesity with increased leptin, glucose, insulin, and glucocorticoid level." (PMID 20844591, 2010).
Hypertension (continued). "It has been proposed that leptin, the most abundant adipose-specific protein, plays a central role in inducing hypertension." (PMID 21274292, 2009). "In total, 12 markers in 7 genes (ADRA2A, LEP, LEPR, PTGER3, SLC2A1, SLC4A2, SLC8A1) revealed considerable association (P<10−3) either with SBP, DBP, and/or hypertension (HYP)." (PMID 19562039, 2009). "In the present investigation, we report a genetic association study on obese and hypertension using three candidate loci (ApoB, LPL and Leptin)." (PMID 19772655, 2009). "Among the adipocytokines involved in the pathogenesis of hypertension, adiponectin and leptin have been most extensively studied." (PMID 19754934, 2009). "Our study is designed to explore the relationship between leptin and norepinephrine levels in pediatric patients and to identify any contributors to hypertension for this population." (PMID 21274292, 2009). "Leptin’s proatherogenic effects include the development of hypertension, oxidative stress, endothelial dysfunction, inflammation, platelet aggregation, migration, proliferation and hypertrophy of VSMC." (PMID 20066136, 2008). "Administration of α-blockers abolished leptin-induced hypertension, supporting a role for the SNS in the development of hypertension." (PMID 20066136, 2008). "Leptin enhances hypertension through the activation of the RAAS and increased sympathetic activity." (PMID 40724891, 2025). "In MCI participants, fasting leptin did not predict 3-year dementia risk after adjustment for BMI, hypertension, insulin, and C-reactive protein." (PMID 41516046, 2025). "Additionally, prior research has indicated the effect of LEP on regulating vascular function and its potential role in the onset of hypertension, a characteristic feature of PE." (PMID 39967661, 2025). "Hyperleptinemia, leptin resistance, and hypoadiponectinemia are, in fact, amongst the crucial pathophysiological pillars for the development of not only IR but also of atherosclerosis and arterial hypertension." (PMID 40137089, 2025). "Mouse studies have also shown that leptin can induce hypertension and endothelial dysfunction via aldosterone pathways rather than the sympathetic system in obese females, providing evidence for sexually dimorphic roles of adipose tissue in the context of the pathophysiology of hypertension." (PMID 39858537, 2025). "The C allele (64Arg) carriers of rs4994T/C SNP significantly increase serum TG, TC, and leptin levels but decrease HDL-C and adiponectin concentrations mainly among obese Asian women, and are associated with an increased risk of essential hypertension in the Chinese and Caucasian population." (PMID 41272565, 2025). "Similar to other atypical antipsychotics, olanzapine use has been connected with various metabolic effects such as weight gain, accumulation of visceral fat, hyperlipidemia, increased blood leptin levels, insulin resistance, diabetes type 2, and high blood pressure." (PMID 40969408, 2025). "Hypertension is believed to result from the sympathetic system activation commonly found in obese patients, affecting peripheral resistance or blood flow in the kidneys, along with elevated leptin levels in these individuals." (PMID 38397015, 2024). "In addition, leptin can stimulate the activity of the sympathetic nervous system, leading to hypertension." (PMID 39062887, 2024). "Finally, in female mice, leptin induces endothelial dysfunction and hypertension via the leptin–aldosterone–endothelial MR axis." (PMID 38186879, 2024). "Leptin is primarily secreted by subcutaneous adipose tissue, whereas other inflammatory markers, such as IL-6 are 2-to-3 times higher in visceral adipose tissue when compared to subcutaneous adipose tissue and also contribute to hypertension development." (PMID 37872379, 2024). "Furthermore, elevated leptin levels were found to be an important predictor of cardiovascular-related death and hypertension." (PMID 38254811, 2024).
Hypertension (continued). "In the context of cardiovascular health, it has been established that leptin promotes hypertension through distinct mechanisms based on sex: it triggers sympathetic nervous system activation in men and stimulates the aldosterone–mineralocorticoid receptor pathway in women." (PMID 39335491, 2024). "Paradoxically, elevated leptin levels may contribute to dysfunction in pancreatic β-cells and hypertension, though the role of leptin in these conditions remains controversial." (PMID 39684879, 2024). "Furthermore, after the local application of TRPM7 blocker FTY720 or TRPM7 shRNA in CB, it was found that it inhibited leptin-induced hypertension effectively." (PMID 38255767, 2024). "In contrast, hypertension inhibits the leptin-induced heart contractile response." (PMID 39407987, 2024). "The autoimmune disease systemic lupus erythematosus (SLE) is characterized by imbalances in various cytokines, including the adipokine leptin, which may play a role in immune system dysfunction and the development of hypertension." (PMID 38031726, 2023). "In the present study, we hypothesized that leptin antagonism would improve B- and T-cell dysfunction and attenuate hypertension in an experimental model of SLE, the NZBWF1 mouse." (PMID 38031726, 2023). "Increased matrix proliferation, neovascularization via vascular endothelial growth factor, promotion of vascular calcifications through vascular smooth muscle cell differentiation to osteoblast cells and prothrombotic effects of leptin all contribute to increased hypertension." (PMID 37371050, 2023). "Some studies also consider the possibility of leptin to predict the onset of hypertension." (PMID 36985762, 2023). "Ang II, leptin and NE played a key role in the development of hypertension." (PMID 36925479, 2023). "This study comprehensively evaluated the changes of inflammation caused by high-salt diet in rats from the aspects of inflammatory cytokines (TNF-α, IL-8, IL-1β, and IL-6) and hormones related to hypertension (NE, LEP, and Ang II), and Vascular and renal lesions were also examined." (PMID 36925479, 2023). "Regarding the role of leptin in gestational hypertension and PE, it has been observed that, in a murine model, leptin infusion in mid-pregnancy induces endothelial dysfunction and hypertension." (PMID 37834125, 2023). "Several mechanisms may lead to hypertension, such as insulin and leptin resistance, perivascular adipose tissue dysfunction, renal impairment, renin-angiotensin-aldosterone activation, and sympathetic nervous system activity." (PMID 36348493, 2022). "Moreover, the presence of hypertension for more than 20 years was found to be associated with a decrease in the level of ADIPOQ and increase in LEP within all AT types." (PMID 36157437, 2022). "In hypertension, the expression of LEP increases in EAT, which, given the possible proliferative effect of leptin and the effect on vascular permeability, may contribute to the progression of this disease." (PMID 36157437, 2022). "Notably, both IR and elevated leptin levels are strongly correlated to hypertension, which is indicated in the present study by significantly elevated SBP levels." (PMID 36418417, 2022). "These include high blood pressure, aberrant serum lipids (high cholesterol, triglycerides, and atherogenic lipoproteins) and elevated serum glucose and pro-inflammatory serum markers, such as adipokines (e.g., leptin) and C-reactive protein (CRP)." (PMID 35268057, 2022). "In addition, levels of leptin are higher in obese individuals than in lean ones, leptin can induce hypertension by enhancing TRPM7 channel expression in the carotid body glomus cells and increasing TRPM7 activity." (PMID 33716794, 2021). "The underlying biological mechanisms may be explained as a high-fat-diet-induced sensitization of angiotensin-II-elicited hypertension is mediated by leptin through the upregulation of the central renin–angiotensin system and proinflammatory cytokines." (PMID 34886102, 2021).
Hypertension (continued). "Additionally, the melanocortin system is an important mediator of the leptin- and insulin-induced forms of hypertension." (PMID 34512392, 2021). "In lean persons, leptin induces satiety and energy expenditure, whereas, in the obese person, there is leptin resistance despite high leptin levels, which goes on to suppress the secretion of insulin from B islet cells of the pancreas and promotes hypertension." (PMID 34109302, 2021). "Moreover, leptin is involved in blood pressure regulation, and obese patients usually have hypertension." (PMID 34202775, 2021). "At the same time, elevated plasma leptin levels may increase blood pressure and contribute to the development of hypertension." (PMID 34068919, 2021). "First, increasing leptin leads to hypertension via increasing the sympathetic nervous system (SNS)." (PMID 35186858, 2021). "However, they also reported serum leptin was positively correlated with BMI, hypertension, and female gender in the patients." (PMID 32968377, 2020). "Hypertension increases ROS production in VSMCs, and this is partly mediated by leptin." (PMID 32566092, 2020). "The subcutaneous fat releases leptin, which may activate the aldosterone–mineralocorticoid receptor axis and contribute to the development of hypertension." (PMID 34095697, 2020). "In females, a role for leptin-induced sympathoexcitation in DIO hypertension is unlikely, but is currently unknown." (PMID 32160920, 2020). "In addition, leptin correlated positively with BMI, total cholesterol and triglycerides in the group with normal-weight hypertension, and with age, diastolic blood pressure, ghrelin and adiponectin in the mild hyperlipidemia group." (PMID 32085704, 2020). "For instance, increased leptin levels can lead to increased aldosterone secretion, endothelial dysfunction, increased vascular stiffness, hypertension, and cardiac hypertrophy, all of which could contribute for AF pathogenesis." (PMID 32782636, 2020). "Increased plasma leptin levels were observed in patients with essential hypertension." (PMID 33192583, 2020). "In addition, for patients with coronary artery disease and VO, against hypertension, hyperleptinemia, leptin resistance, and a reduction in adiponectin concentration were recorded." (PMID 31173592, 2019). "Leptin resistance is a phenomenon also associated with sympathetically mediated BP elevations in other animal models; so leptin resistance may also contribute to the hypertension in this strain." (PMID 31681017, 2019). "Increased circulating leptin levels are present in animals and humans with hypertension." (PMID 31236708, 2019). "In obese subjects, several mechanisms may lead to hypertension such as insulin and leptin resistance, perivascular adipose tissue dysfunction, renal impairment, renin-angiotensin-aldosterone-system activation and sympathetic nervous system activity." (PMID 31330870, 2019). "However, the MHO individuals with high leptin or a high L:A ratio were significantly more likely to developing hypertension when compared with metabolically healthy normal-weight individuals with normal adipokine levels." (PMID 29093301, 2018). "Indeed, mice with a specific deletion of melanocortin-4 receptors in the paraventricular nucleus of the hypothalamus were protected from sympathetic over-activation by maternal leptin and consequently hypertension." (PMID 29635288, 2018). "In contrast, elevated leptin levels areassociated with MetS, hypertension and atherosclerosis." (PMID 30226908, 2018). "Recent findings even indicate that leptin, the adipocyte-derived hormone, may increase the aldosterone production in obese individuals contributing to the development of hypertension." (PMID 29382124, 2018). "Overall, current data show that circulating leptin levels are increased in IH and suggest that hyperleptinemia may be implicated in adverse effects of OSA, such as increased oxidative stress and hypertension." (PMID 29675134, 2018).